SST (somatostatin)
Diseases named in the same sentence as SST in open-access papers (continued):
Sharing a sentence is not in itself a finding about the gene and the disease.
tumor (continued). "Doxorubicin has been chemically conjugated to a number of other peptides, including cell penetrating peptides (CPP), tumor homing peptide Lyp-1, RGD peptides, somatostatin, and bombesin/gastrin-releasing peptide (BN/GRP), and broadly studied." (PMID 31091786, 2019). "Cell cultures from 15 human pNETs were shown to retain in vitro SST expression profile (predominantly SST2) and a secretory phenotype (CgA) of the original tumor, and were used to explore and compare the biological activity of OCT and PAS." (PMID 31412614, 2019). "The current findings provide novel direct epigenetic evidence for the involvement of SST, TAC1, hypocretin neuropeptide precursor (HCRT), neuropeptide Y (NPY), and GAL in the process of tumor suppression in humans." (PMID 29682090, 2018). "SST itself attenuates Insulin Growth Factor 1 (IGF-1) signaling and IGF-1 Receptor (IGF-1R) is important in GEP-NET tumor growth factor biology." (PMID 29973528, 2018). "The clinical presentation of functioning tumours depends on the peptide hormone being secreted such as insulin, gastrin, glucagon, vasoactive intestinal peptide (VIP) and somatostatin." (PMID 31447997, 2018). "We determined, by conventional RT-PCR, if somatostatin (SST) and its receptors (SSTR1-5) are expressed in SW480 and HT29 cells as well as in matched fresh normal and tumor human colon tissue samples." (PMID 27927191, 2016). "The methylation statuses of the promoters of 11 tumor-related genes (p16, RASSF1A, E-cadherin, H-cadherin, MGMT, DAPK, DCC, COL1A2, TAC1, SST, and GALR1) were analyzed in 133 HNSCC cases using quantitative methylation-specific PCR." (PMID 27027429, 2016). "Of note, on comparison of both KO mice models there was a strikingly higher proportion of MG tumors, and higher tumor multiplicity, in LF-fed CORT-KO compared to LF-fed SST-KO mice." (PMID 26956474, 2016). "Studies have demonstrated that the microvascular endothelial cells of tumor tissues sometimes express SSTR and somatostatin." (PMID 27825139, 2016). "SST analogs are able to inhibit the growth of Swarm chondrosarcoma, used as experimental model of SSTR free tumor." (PMID 24570674, 2014). "Among these gene promoters are those involved in tumor suppression (RYBP, APEX, SST, OAS1) as well as oncogenes involved in positively aiding tumor progression (ARGH, FHX)." (PMID 23704879, 2013). "The authors also documented a significant correlation between the histological type of the tumor and the biological properties of the molecules it produces, i.e., MLT, serotonin, and somatostatin, all having an antiproliferative activity." (PMID 23348932, 2013). "As a matter of fact, SST analogues are able to inhibit the growth of Swarn chondrosarcoma, used as experimental model of SSTR free tumour." (PMID 20196864, 2010). "Three (NNAT, SST and NPTX1) of the 7 hypermethylated gene promoters have been reported to be methylated in tumours previously." (PMID 19025626, 2008). "Recently, we developed a series of targeted cytotoxic conjugates based on analogues of peptide hormones such as luteinizing hormone-releasing hormone(LH-RH), somatostatin and BN/GRP, for which high affinity receptors are expressed on a variety of tumours." (PMID 11953892, 2002). "Tumor cells are large with abundant granular eosinophilic to basophilic cytoplasm and regular round nuclei, positive for somatostatin, CK7, MUC1, and SSTR5 and negative for SSTR2A." (PMID 40668487, 2025). "Moreover, somatostatin analogs, peptide receptor radionuclide therapy (PRRT), and molecular targeted drugs have shown effectiveness in controlling tumor growth and alleviating clinical symptoms." (PMID 41403981, 2025). "PanNETs represent a heterogeneous group of tumours, presenting either as hormonally active tumours (producing gastrin, insulin, glucagon, somatostatin, vasoactive intestinal peptide or growth hormone-releasing hormone) or as non-functioning tumours." (PMID 39949334, 2025).
tumor (continued). "Immunohistochemistry showed the tumor cells were diffusely positive for synaptophysin and chromogranin, negative for p40, and focally positive for somatostatin in approximately 5% of tumor cells." (PMID 40336855, 2025). "Other recently investigated parameters are tumor volumes, mostly total receptor volume (RTV), referring to the summed SST-volumes of the segmented lesions, and total lesion activity (TLA), calculated by the sum of the product of each lesions’ SUVmean and its corresponding SST-expressing volume." (PMID 38581469, 2024). "The variation in their responses to treatments such as somatostatin analogs, peptide receptor radionuclide therapy (PRRT), chemotherapy, and immunotherapy also underscores the biological differences between the two tumor types and argues against a universal treatment approach." (PMID 38539512, 2024). "Upon immunohistochemical analysis (IHC), tumor cells stained positively for secretin, glicentin, gastrin, and somatostatin, albeit the latter was not ubiquitously expressed among the cells." (PMID 39649120, 2024). "The suppression of tumour growth by SST and its analogs has also been reported independent of SSTR subtypes." (PMID 38203605, 2023). "SST analogs, however, are not so effective in controlling tumour size: only 5% of patients have tumour regression while 40–60% of patients show tumour stabilization." (PMID 38203605, 2023). "The indirect effect of SST may be due to the inhibition of the growth factors such as IGF-1 gene expression, which indirectly inhibits the levels of IGF-1 overexpressed during tumour development." (PMID 38203605, 2023). "All genes were lowly expressed in tumor samples, except for DEFB1 and SST." (PMID 37318692, 2023). "Both preclinical and clinical studies demonstrated much higher tumor accumulation of these non-internalizing SST analogues than for SSTR agonists." (PMID 36952073, 2023). "An interesting alternative could be the somatostatin antagonist, [177Lu]Lu-DOTA-JR11, that demonstrated better biodistribution profile and higher tumor uptake than [177Lu]Lu-DOTA-TATE." (PMID 37389800, 2023). "Preclinical studies demonstrated much higher tumor accumulation of these non-internalizing SST analogues than for SSTR agonists." (PMID 34625828, 2022). "An alternative imaging technique is a somatostatin-seeking nuclear medicine study, as the majority of MCC (85%) exhibits somatostatin receptors on the tumor cell surface, which may be useful to differentiate from other malignant etiologies." (PMID 36497395, 2022). "Moreover, considering the differences observed in the peritumoral region and also the fact that the migration of somatostatin and parvalbumin is controlled by different signaling pathways during brain development, its final position may be also controlled by different effects from tumor tissue." (PMID 36538906, 2022). "That discrepancy might be due to the high heterogeneity of SST and CXCR4 expression among individual tumours, which was visible in the whole-block tumour samples." (PMID 35799158, 2022). "SST analogues (Octreotide, Lanreotide, and Pasireotide (for SSTR2,5)) are widely used as first-line treatment for perioperative period, metabolic diseases, and tumor control." (PMID 33796080, 2021). "The availability of organoids and spheroids may finally allow the study of downstream targets of somatostatin and IGF2 in I-NETs as well as the importance of candidate tumor genes like MIR1-2, RASSF1A, APC, or CDKN1B." (PMID 34680217, 2021). "Together, these findings suggest a potential difference in effect between mifepristone and relacorilant, in which relacorilant-induced increased SSTR2 expression on the tumor can increase the efficacy of endogenous and exogenous somatostatin on ACTH secretion and tumor proliferation." (PMID 35058882, 2021).
tumor (continued). "SSTR receptors have been exploited as therapeutic targets for NETs given that their activation suppresses hormone secretion in several SST target tissues, as well as inhibits the proliferation of normal and tumor cells." (PMID 34205778, 2021). "Sixty-nine percent of patients had not undergone any previous anti-tumor treatment, 31% had undergone a large variety of previous treatments, mainly consisting of somatostatin analogs, radioisotopes, chemotherapy, and targeted therapy." (PMID 34326338, 2021). "The unaltered CGRP, SP and somatostatin levels observed in the tumor tissue of desensitized mice indicate significant non-neural sources of these mediators." (PMID 34336669, 2021). "The 161Tb- and 177Lu-labeled somatostatin (SST) analogues DOTATOC (agonist) and DOTA-LM3 (antagonist) were tested in vitro to demonstrate equal properties regarding distribution coefficients and cell uptake into SST receptor-positive AR42J tumor cells." (PMID 33921467, 2021). "[68Ga]Ga-DOTA-ST8950 showed high uptake in both SST2- and SST5-expressing tumors, similar to [68Ga]Ga-DOTA-NOC (p = 0.4630 for SST2 and p = 0.3282 for SST5), proven to be receptor subtype mediated by the 90% reduction found on the SST-negative tumor." (PMID 32757150, 2020). "In contrast, treatment with comparable doses of a pure DA analogue, a pure SST analogue, or the combination of the two, had no statistically relevant effect on tumor growth and were not distinguishable from vehicle-only treatment." (PMID 32591776, 2020). "The pituitary weights in DA agonist-treated, SST agonist-treated, and the combination were not significantly different from the pituitaries from untreated, tumor-bearing controls after 8 weeks." (PMID 32591776, 2020). "A most interesting result was the fact the SST hypermethylation and concomitant downregulation occurred in tumor DNA but not in material isolated from CP patients, which showed similar methylation variations but a different response at the transcript level." (PMID 32243066, 2020). "Immunohistochemically, tumour cells stained markedly positive for somatostatin (95%) and insulin (5%); interestingly, staining for the two hormones was restricted to distinct cell populations and not uniform throughout the tumour." (PMID 31592116, 2019). "It makes no sense to treat patients with SST analogues if the tumor does not express SSTRs at all, or only SSTRs for which the SST analogue has no or low affinity." (PMID 31569719, 2019). "Although SSTR2 has its specific endogenous ligand (somatostatin) but it is not much involved in tumor growth inhibition and therapy." (PMID 29029435, 2017). "That SST and SSTR1 were always expressed in the normal colonic epithelial cells, and SST was completely lost in the tumor cells while SSTR1 was also expressed in the tumor cells of some patients is an important finding." (PMID 27927191, 2016). "When we analyzed additional normal tissue samples (ones without matched tumor), the results still showed presence of SST expression in all samples analyzed (data not shown)." (PMID 27927191, 2016). "Of these, CAV1, SFRP2, TMEFF2, SST and SLIT2 have been identified as tumor-suppressor genes." (PMID 25997610, 2015). "Although not easily detected in many in vitro cultured tumor cells, binding affinities in 5 tumor cells were further investigated with SST-14 which has high affinity to all 5 SSTR subtypes." (PMID 21892324, 2008). "We observed that treatment with either DOX or SST alone did not significantly inhibit tumor growth in contrast to co-treatment with DOX and the lower concentration (1 mg/kg) of SST." (PMID 17617924, 2007). "Specific high-affinity receptors for bombesin and somatostatin were found on membranes of SCLC H69 tumours, but not on non-SCLC H157 tumours." (PMID 7947094, 1994).
tumor (continued). "Unfortunately, SST signaling was not analyzed in any of these studies thus not allowing conclusions as to whether SSTR2 signaling crosstalks with TβRII or ALK5 in tumor suppression or with ALK5 in metastasis promotion." (PMID 40134804, 2025). "There was also a tendency for a higher uptake in some tissues (e.g. pancreas, tumor) for the [188Re]Re-labeled analogs in comparison with the ones labelled with Tc-99 m, especially for GRPR-expressing tissues, a trend also shown for PSMA and somatostatin analogs." (PMID 39825204, 2025). "For example, a stable lesion may mask intralesional de-differentiation while a decrease in tumor volume after chemotherapy could subtend a cyto-reductive effect on the most aggressive components without a significant effect on SST-expressing cells." (PMID 38581469, 2024). "According to the European Neuroendocrine Tumor Society recommendations, PRRT could be a valid strategy in case of a high SST expression; everolimus could also be considered, especially in cases with low SST expression." (PMID 38634006, 2024). "The hypothesis of an occult neuroblastic tumor is not always considered, which delays or impairs treatment, which consists of surgery, chemotherapy, the use of somatostatin analogs, or somatostatin itself." (PMID 39328672, 2024). "Therefore, the somatostatin-mediated effects do not explain the post-treatment increase in catecholamine/metanephrine levels that most likely occurs due to radiation-related tumor disruption." (PMID 37886645, 2023). "In the present study, we could not confirm that somatostatin expressing tumour volume on 68Ga‐DOTA‐TATE/TOC in patients with metastatic GEP‐NET, measured as either ∑SRETV or ∑TLSRE, was associated with HRQoL." (PMID 35488399, 2022). "However, the role of SST signalling and SSTR in NET development, the response to SSA, and prognosis highly depends upon SSTR distribution in different tumour types and additional intrinsic factors of specific tumours." (PMID 35163374, 2022). "One plausible answer could be that an SSTR, in the absence of exogenous SSA, still receives endogenous somatostatin signals and this slows the tumour progression." (PMID 35163374, 2022). "Indeed, terbium-161 was more effective in reducing AR42J tumor cell viability and survival than lutetium-177, irrespective of the SST analogue employed." (PMID 34625828, 2022). "However, the authors were unable to validate a reduction in SST mRNA expression in human tissue using 10 pairs of tumor and adjacent non-tumorous tissue (p = 0.074)." (PMID 33085037, 2021). "Increased intra-tumoral SST expression may in turn lead to anti-secretory and anti-proliferative effects, whereas increased SSTR2 expression could improve tumor visibility with SSTR-scintigraphy and enhance tumor response to (radiolabeled) SSAs." (PMID 33085037, 2021). "Furthermore, SST-expressing tumors can have different biological characteristics than tumors without SST expression, even within the same tumor type, as SST expression suggests neuroendocrine differentiation of tumors." (PMID 32335823, 2020). "Beyond the rapid in vivo clearance of the pure SST analogue, the reasons why the pure DA and SST agonists inhibit NFPA cell proliferation in vitro but do not have a significant effect on tumor growth in the POMC KO mice is unknown." (PMID 32591776, 2020). "Tumor size was not related to the expression of any of SST subtypes." (PMID 31336364, 2019). "Other reasons for the absence of a significant effect of SST analogues on tumor progression and survival could be resistance to SST analogues, including desensitization of the receptor or the presence of a spliced SSTR5 variant." (PMID 31569719, 2019). "Therefore, the detection of methylation in the genes SST, TAC1, SEPT9, and HLTF may enable early detection and assist in more effective intervention during postresection tumour recurrence compared to conventional markers." (PMID 29038612, 2017).
tumor (continued). "Immunohistochemically, the tumor was strongly positive for keratin 7 (CK7) and pankeratin AE1/AE3, and alpha 1 antichymotrypsin; negative for synaptophysin and chromogranin A, CDx2, CK20, S100, carcinoembryonic antigen (CEA), MUC 2, MUC5AC, and somatostatin; and in part positive for CA19-9." (PMID 29145864, 2017). "While all normal samples expressed SST, SST expression was absent in all matched tumor samples." (PMID 27927191, 2016). "Interestingly, SST was expressed in all the normal tissue samples, but not expressed in the matched tumor tissues." (PMID 27927191, 2016). "However, no unanimity exists about the SST analog ability to control (i.e., to slow) the tumor progression." (PMID 24570674, 2014). "SST controls cancer cell proliferation via the interference with different signaling pathways (PTPs, JAK2, Ras/ERK, and Pi3K/Akt) resulting in cytostatic effects mediated by the induction of involving the induction of cell cycle inhibitors p27 or p21, or tumor suppressors, like Zac1." (PMID 23476673, 2013). "However, we saw that there was no glucagon or somatostatin staining of tumor cells in PDICs, indicating that PDICs lack expression of all pancreatic neuroendocrine cell type-specific markers." (PMID 23691228, 2013). "Peptide receptor radionuclide therapy (PRRT) in somatostatin-positive NETs is a replacement treatment strategy in patients who are not suitable for radical resection, and PRRT could result in disease stabilization, partial remission, or reduction of tumor mass." (PMID 35350567, 2022). "Independent of the presence or absence of expression in the tumour cells, SST and CXCR4 were often strongly expressed on the tumour capillaries." (PMID 35799158, 2022). "Immunohistyochemically, tumor cells were positive for cytokeratin, synaptophysin, neuron-specific enolase, and CD56; they were negative for chromogranin, gastrin, glucagon, somatostatin, pancreatic polypeptide, and vasoactive intestinal polypeptide." (PMID 27990210, 2009). "A tumour‐produced incretin could not be identified (we checked for GLP‐1, CCK, pro CCK and GIP), but somatostatin levels were markedly increased in the basal state (5 nmol/L, normal <0.1) and decreased during the glucose challenge." (PMID 31592116, 2019).